PUSL1 (pseudouridine synthase like 1)
Description:
Pseudouridylate synthase that catalyzes the conversion of uridine to pseudouridine in mitochondrial tRNAs. Acts on position 38/39/40 in the anticodon stem of mitochondrial tRNAs.
Synonyms: FLJ90811
Tractability: PROTAC: ubiquitination databases record sites on it.
Gene: Protein-coding gene on chromosome 1 (1,308,567 to 1,311,677, forward strand). Ensembl gene ENSG00000169972.
Subcellular location: Mitochondrion matrix; Mitochondrion inner membrane
Subcellular location (Human Protein Atlas): Vesicles
Gene Ontology:
Molecular function: tRNA pseudouridine(38-40) synthase activity; tRNA pseudouridine synthase activity; pseudouridine synthase activity; RNA binding
Biological process: tRNA pseudouridine synthesis; mRNA pseudouridine synthesis; pseudouridine synthesis; RNA modification
Cellular component: mitochondrion; mitochondrial matrix; mitochondrial inner membrane
Genetic constraint (gnomAD): Loss-of-function variants: 51 observed, 24.72 expected, observed/expected ratio (o/e) 2.06. The synonymous counts are far from expectation, so gnomAD's model fits this gene poorly and the ratio says little. Missense variants: 609 observed, 363.38 expected, observed/expected ratio (o/e) 1.68, 90% interval 1.57 to 1.79. Synonymous variants: 290 observed, 168.23 expected, observed/expected ratio (o/e) 1.72, 90% interval 1.57 to 1.89.
Homologues: Orthologues: chimpanzee PUSL1 (99% identical), macaque PUSL1 (95% identical), dog PUSL1 (80% identical), guinea pig PUSL1 (79% identical), mouse Pusl1 (77% identical), rat Pusl1 (74% identical), pig PUSL1 (65% identical), tropical clawed frog pusl1 (50% identical), zebrafish pusl1 (44% identical), Drosophila melanogaster CG34140 (30% identical), Caenorhabditis elegans Y73B6BL.29 (18% identical). Paralogues in human: PUS3 (24% identical), PUS1 (22% identical).
Diseases named in the same sentence as PUSL1 in open-access papers:
PUSL1 is named in the same sentence as 5 diseases in open-access papers, as found by Europe PMC text mining. Sharing a sentence is not in itself a finding about the gene and the disease. The quoted sentences say what the papers report.
breast carcinoma (1 paper, 2021). "We searched the search interface for the survival of XIST and PUSL1 in GSE42568 (breast cancer expression profile) and found that the HR value of XIST was <1, while the Cox p-value was less than 0.05." (PMID 34113575, 2021).
Tumor (3 papers, 2018 to 2024). "We initially calculated the univariate and multivariate analysis of overall survival (OS) rate, including the expression of genes belonging to the PUS family (PUS1, PUS3, PUS7, PUS10, PUS7L, PUSL1), patients’ age, gender, race and Tumor Node Metastasis (TNM)-stage, and set grade as co-variate." (PMID 37315299, 2023). "Strikingly, patients exhibiting elevated levels of PUS1, PUS3, PUSL1, RPUSD1-4, and TRUB2 demonstrated a significantly shorter disease-free survival, as evidenced by combined analysis with tumor disease-free survival data." (PMID 39247811, 2024).
PUSL1 also shares sentences with these, for which no sentence is quoted: cancer (1 paper); prostate adenocarcinoma (1); prostate carcinoma (1).